APPL1 (adaptor protein, phosphotyrosine interacting with PH domain and leucine zipper 1)
Description:
Multifunctional adapter protein that binds to various membrane receptors, nuclear factors and signaling proteins to regulate many processes, such as cell proliferation, immune response, endosomal trafficking and cell metabolism. Regulates signaling pathway leading to cell proliferation through interaction with RAB5A and subunits of the NuRD/MeCP1 complex. Functions as a positive regulator of innate immune response via activation of AKT1 signaling pathway by forming a complex with APPL1 and PIK3R1 (By similarity). Inhibits Fc-gamma receptor-mediated phagocytosis through PI3K/Akt signaling in macrophages (By similarity). Regulates TLR4 signaling in activated macrophages (By similarity). Involved in trafficking of the TGFBR1 from the endosomes to the nucleus via microtubules in a TRAF6-dependent manner. Plays a role in cell metabolism by regulating adiponecting and insulin signaling pathways. Required for fibroblast migration through HGF cell signaling (By similarity). Positive regulator of beta-catenin/TCF-dependent transcription through direct interaction with RUVBL2/reptin resulting in the relief of RUVBL2-mediated repression of beta-catenin/TCF target genes by modulating the interactions within the beta-catenin-reptin-HDAC complex.
Synonyms: APPL; DIP13alpha; MODY14
Tractability: Small molecule: it has a high-quality binding pocket. Antibody: UniProt places it where antibodies can reach, with high confidence; its Gene Ontology location is reachable by antibodies, with high confidence; the Human Protein Atlas places it where antibodies can reach. PROTAC: ubiquitination databases record sites on it; its protein half-life has been measured.
Gene: Protein-coding gene on chromosome 3 (57,227,726 to 57,278,127, forward strand). Ensembl gene ENSG00000157500.
Subcellular location: Early endosome membrane; Nucleus; Cytoplasm; Endosome; Cell projection, ruffle; Cytoplasmic vesicle, phagosome
Subcellular location (Human Protein Atlas): Plasma membrane; Vesicles; Actin filaments; Cytosol
Pathways (Reactome):
Programmed Cell Death: Caspase activation via Dependence Receptors in the absence of ligand
Gene Ontology:
Molecular function: beta-tubulin binding; identical protein binding; phosphatidylinositol binding; phosphatidylserine binding; protein binding; protein homodimerization activity; protein kinase B binding; protein-containing complex binding
Biological process: adiponectin-activated signaling pathway; insulin receptor signaling pathway; maintenance of synapse structure; positive regulation of D-glucose import; positive regulation of melanin biosynthetic process; protein import into nucleus; regulation of D-glucose import; regulation of G1/S transition of mitotic cell cycle; regulation of protein localization to plasma membrane; transforming growth factor beta receptor signaling pathway; cellular response to hepatocyte growth factor stimulus; negative regulation of Fc-gamma receptor signaling pathway involved in phagocytosis; positive regulation of cytokine production involved in inflammatory response; positive regulation of macropinocytosis; regulation of fibroblast migration; regulation of innate immune response; regulation of toll-like receptor 4 signaling pathway; signal transduction; signaling; positive regulation of transport
Cellular component: cytoplasm; cytoplasmic vesicle; cytosol; early endosome; early endosome membrane; endosome; endosome membrane; extracellular exosome; glutamatergic synapse; intracellular vesicle; membrane; nucleus; plasma membrane; vesicle membrane; early phagosome; macropinosome; ruffle; phagocytic vesicle
Genetic constraint (gnomAD): Loss-of-function variants: 24 observed, 64.4 expected, observed/expected ratio (o/e) 0.37, 90% interval 0.27 to 0.52. The upper end of that interval is the gene's LOEUF score, 0.52, which puts it in group 2 of 6, group 1 being the genes least tolerant of losing a copy. Missense variants: 535 observed, 600.97 expected, observed/expected ratio (o/e) 0.89, 90% interval 0.83 to 0.96. Synonymous variants: 196 observed, 205.04 expected, observed/expected ratio (o/e) 0.96, 90% interval 0.85 to 1.08.
Gene-disease validity (ClinGen):
ClinGen rates the evidence that APPL1 causes each of these diseases.
monogenic diabetes (autosomal dominant): Refuted. Diabetes mellitus that is caused by mutations in a single gene.
Homologues: Orthologues: chimpanzee APPL1 (100% identical), dog APPL1 (98% identical), rabbit APPL1 (98% identical), mouse Appl1 (98% identical), rat Appl1 (97% identical), macaque APPL1 (97% identical), pig APPL1 (97% identical), guinea pig APPL1 (95% identical), tropical clawed frog appl1 (84% identical), zebrafish appl1 (80% identical). Paralogues in human: APPL2 (50% identical), GIT1 (18% identical), GIT2 (18% identical), ARAP3 (12% identical), ASAP1 (11% identical), ARAP1 (11% identical), ARAP2 (11% identical), ASAP2 (10% identical), ARFGAP3 (8% identical), ACAP3 (8% identical), ASAP3 (8% identical), ACAP1 (7% identical), and 16 more.
Diseases named in the same sentence as APPL1 in open-access papers:
APPL1 is named in the same sentence as 69 diseases in open-access papers, as found by Europe PMC text mining. Sharing a sentence is not in itself a finding about the gene and the disease. The quoted sentences say what the papers report.
diabetes (13 papers, 2013 to 2025). "Given the function of this gene and its implication in MODY type 14, APPL1 is a potential cause of diabetes in this patient." (PMID 35246208, 2022). "APPL1 deficiency is an important molecular mechanism contributing to diabetes mellitus, and APPL1 plays an important role in alleviating insulin resistance and resisting diabetes." (PMID 35984564, 2022). "Further research on rs11544593 in a larger study population and identification of polymorphisms of the genes encoding binding partners of APPL1 in signaling cascades hold promise for elucidation of the pathogenesis of diabetes phenotypes." (PMID 32854233, 2020). "Five participants presented other monogenic diabetes mutations (HNF1B: n = 2; PDX1: n = 2; APPL1: n = 1) but were excluded from the analysis." (PMID 35822264, 2022). "In the liver, APPL1 potentiates the inhibitory effect of insulin on hepatic gluconeogenesis through activation of AKT protein kinases; APPL1 overexpression in the liver eliminates hyperglycemia in mice with diabetes." (PMID 32854233, 2020). "ZDF rats as a model of diabetes mellitus type 2 are characterized by hypoadiponectinemia, a reduced expression of APPL1 and a decreased response of their mesenteric arteries to adiponectin and acetylcholine in terms of endothelial dysfunction." (PMID 23497197, 2013). "To investigate whether THC restores adiponectin-mediated function in the pancreas in diabetes, we examined AdipoR1 and APPL1 levels with immunofluorescence staining." (PMID 34960104, 2021). "Here, an analysis of APPL1 was performed in patients with a maturity-onset diabetes of the young (MODY) phenotype, and prevalence of these mutations was estimated in a Russian population, among type 2 diabetes mellitus (T2DM) and MODY patients." (PMID 32854233, 2020). "Although future studies are needed to elucidate the effects of physical exercise on the liver, it seems clear that, when performed regularly, it can play an important role in preventing the development of insulin resistance and diabetes through the APPL1/TRB3/Akt pathway." (PMID 26288661, 2015). "However, despite its LOD score being comparable to the low-penetrance control, in the APPL1 pedigree, more than 10% of family members aged 25 or older without diabetes carried the variant (binomial p = 0.001)." (PMID 40779032, 2025). "Whether GLP-1 agonists promote APPL1-AMPK-PPARα signaling to decrease NF-κB expression and cardiomyocyte apoptosis in diabetes is still unknown." (PMID 26759813, 2016).
Insulin resistance (13 papers, 2012 to 2024). Increased resistance towards insulin, that is, diminished effectiveness of insulin in reducing blood glucose levels. "Our previous studies demonstrated that APPL1 deficiency causes insulin resistance in the liver and endothelium by inhibiting Akt activation." (PMID 34789781, 2021). "Genes encoding adiponectin and adiponectin receptors contribute to insulin resistance and the risk of obesity, and genetic variants of APPL1 are associated with body fat distribution." (PMID 22462604, 2012). "Similarly, hematopoietic cell from APPL1-specific deficient mice showed increased ROS generation, inflammasome activation, and insulin resistance." (PMID 32059381, 2020). "Another theory also indicates IRS1/2-PI3K-Akt signaling, which is activated by an interaction between adiponectin and APPL1 lowering insulin resistance." (PMID 32059381, 2020). "Genome loci based data and population study support that highly connected genes, like ADIPOQ, MAPK3, PLCG1 and APPL1 in the database, play an important role in insulin resistance development." (PMID 29201145, 2017). "Conversely, APPL1 overexpression in the liver increases Akt activation and alleviates insulin resistance in obese mice." (PMID 26655903, 2015). "Our findings demonstrate that exercise training performed concomitantly to a high-fat diet reduces the degree of insulin resistance and improves adipoR1-2/APPL1 protein levels in the hepatic, adipose, and skeletal muscle tissue." (PMID 23046739, 2012). "Taken together, our data demonstrated that exercise training performed concomitantly to feeding with a high-fat diet reduces the degree of insulin resistance and improves adiponectin receptors 1 and 2 and APPL1 protein levels in the hepatic, adipose, and skeletal muscle tissue." (PMID 23046739, 2012). "Positive effects have also been confirmed in vivo as osmotin through activation of the AdipoR1/2, APPL1, AMPK pathway, reduced blood glucose levels, decreased insulin resistance, and increased fatty acid oxidation and mitochondrial function." (PMID 35444544, 2022). "Hematopoietic-specific deletion of APPL1 aggravated HFD-induced glucose intolerance and insulin resistance, as assessed by glucose tolerance test (GTT) and insulin tolerance test (ITT), respectively." (PMID 34789781, 2021). "In contrast, systemic insulin resistance was observed in cases of APPL1-/- mice, and insulin stimulation did not increase the expression level of IRS1/2." (PMID 32059381, 2020). "The aim of the present study was to evaluate the protective effect of concurrent exercise in the degree of the insulin resistance in mice fed with a high-fat diet, and assess adiponectin receptors (ADIPOR1 and ADIPOR2) and endosomal adaptor protein APPL1 in different tissues." (PMID 23046739, 2012). "As one of the insulin-sensitizing fatty factors, APN is secreted by fat cells to improve insulin resistance and attenuate hyperglycemia as well as impair RANKL-stimulated RAW264.7 cells through its receptors as AdipoR1, AdipoR2, and T-Cadherin and its downstream factors of cohesive protein APPL1." (PMID 36632609, 2021). "Additionally, adiponectin signaling (AdipoR2, APPL1, and pAMPK/AMPK ratio) in the liver was found to be impaired in these animals, which could reduce fatty acid oxidation capacity, thereby increasing lipid accumulation and consequently exacerbating insulin resistance." (PMID 39339665, 2024).
MODY (12 papers, 2019 to 2025). "This is further supported by the prevalence of all PTVs in APPL1 in gnomAD, which are too common to be a cause of MODY (combined allele count of 1 in 1,347 in gnomAD v4.1.0)." (PMID 40779032, 2025). "Consequently, we cannot exclude the possibility that APPL1 or WFS1 harbor extremely rare or low-penetrance MODY-causing variants." (PMID 40779032, 2025). "Heterozygous variants in NEUROD1, PDX1, APPL1, and WFS1 have been implicated in MODY, but strong genetic evidence supporting causality is lacking." (PMID 40779032, 2025). "The first reported MODY-associated variants in NEUROD1, PDX1, APPL1, and WFS1 were <1:20,000 frequency." (PMID 40779032, 2025). "Currently, 13 genes on different chromosomes have been designated as MODY-causing genes, although mutations in other genes, such as RFX6 and APPL1, have also been reported to be associated with MODY." (PMID 37711893, 2023). "For the first time, a genetic analysis of the APPL1 gene was performed on Russian patients with early-onset diabetes mellitus that phenotypically corresponds to MODY." (PMID 32854233, 2020). "In conclusion, we provide genetic evidence that NEUROD1 and PDX1 cause low penetrance MODY whereas variants in APPL1 and WFS1 do not cause MODY and should not be included in MODY genetic analysis." (PMID 40779032, 2025). "This remains true even when focusing specifically on the functional domains, reinforcing the idea that PTVs in APPL1 do not cause MODY." (PMID 40779032, 2025). "In this study, we used a large clinically suspected MODY cohort and population controls to assess the genetic evidence for NEUROD1, PDX1, APPL1, and WFS1." (PMID 40779032, 2025). "In all cases, we observed consistent results that APPL1 and WFS1 variants are not enriched in the MODY cohort, whereas NEUROD1 and PDX1 were at a level similar to RFX6." (PMID 40779032, 2025). "In summary, rare heterozygous variants in NEUROD1 and PDX1 are low-penetrance causes of MODY, while those in APPL1 and WFS1 lack robust genetic evidence for causality and should not be included in MODY testing panels." (PMID 40779032, 2025). "Moreover, we also detected variants in rare MODY-related genes, including NEUROD1 (MODY6), KCNJ11 (MODY13) and APPL1 (MODY14), among other MODY subtypes." (PMID 36613572, 2022). "To date, 14 disease genes for MODY are identified; most of them are transcription factors MODY1 (HNF4A), MODY3 (HNF1A), MODY4 (PDX1), MODY5 (HNF1B), MODY6 (NEUROD1/BETA2), MODY7 (KLF11), MODY8 (CEL), MODY9 (PAX4), MODY11 (BLK), and MODY14 (APPL1)." (PMID 31145732, 2019).
prostate carcinoma (11 papers, 2015 to 2025). A carcinoma that arises from epithelial cells of the prostate gland. "The Appl-1, Sortilin, and Syndecan-1 biomarker panel addresses critical diagnostic challenges in prostate cancer pathology by enhancing the accuracy of detection and reproducibility of Gleason grading and ISUP group assignment." (PMID 41465218, 2025). "Appl1, Sortilin and Syndecan-1 are biomarkers within the endosome-lysosome system, and immunohistochemistry (IHC) labelling of these proteins may enable improved visualisation of the complex pathologies underlying prostate cancer." (PMID 37370825, 2023). "The biomarkers Appl-1, Sortilin, and Syndecan-1 represent a transformative advancement in prostate cancer pathology assessment and are now being integrated into clinical practice in the USA." (PMID 41465218, 2025). "A biomarker panel comprising Appl1, Sortilin, and Syndecan-1 has recently been used to define the complex biological changes contributing to prostate cancer pathogenesis and IDCP." (PMID 37704825, 2024). "Tissue samples from 86 patients with prostate cancer were assessed by routine haematoxylin and eosin staining and immunohistochemistry (IHC) with a biomarker panel (Appl1/Sortilin/Syndecan-1) and a PIN4 cocktail (34βE12+P63/P504S)." (PMID 37704825, 2024). "The current study demonstrated that IHC-assisted grading using Appl1, Sortilin and Syndecan-1 biomarkers improved prognostic predictions in patients with prostate cancer compared to H&E." (PMID 37370825, 2023). "Taken together, these observations suggest that the endosomal proteins APPL1 and APPL2 are important for the nuclear trafficking of TβRI-ICD, which is regulated by TRAF6 and is linked to prostate cancer progression." (PMID 26583432, 2016). "We also found that the TGFβ-induced invasion of cancer cells is dependent on APPL1 and APPL2 expression and that the APPL1 expression is increased in malignant prostate cancer tissues compared with normal prostate tissues." (PMID 26583432, 2016). "Using PLA, we detected a significantly higher number of APPL1-TβRI complexes in sections from patients with aggressive prostate cancer compared with less aggressive tumours." (PMID 26583432, 2016). "In tissues from prostate cancer, APPL1 expression was found to correlate with tumour malignancy (Gleason Score), indicating an important functional role for APPL1 in tumourigenesis of prostate cancer." (PMID 26583432, 2016). "In this report, we identify APPL1 as a TβRI- and PKCζ-associated protein and show that APPL1 and APPL2 are required for the nuclear translocation of TβRI-ICD, and thereby promote progression of prostate cancer cells." (PMID 26583432, 2016). "Rather than relying on non-specific associations, Appl-1, Sortilin, and Syndecan-1 directly mirror the underlying biological architecture and primary pathogenesis of prostate cancer." (PMID 41465218, 2025). "Yet, APPL1 was highly expressed in the prostate cancer tissues." (PMID 37273920, 2023). "Interestingly, we also observed a greater number of APPL1-TβRI complexes in more aggressive prostate cancer tissues." (PMID 26583432, 2016). "Furthermore, Appl-1 distinguishes benign tissue through its basal cell distribution, which transitions to a cytoplasmic pattern in malignant cells, offering a pathophysiological basis for its precise detection of prostate cancer." (PMID 41465218, 2025). "Moreover, OT increases prostate cancer growth and induces the expression of APPL1." (PMID 28415720, 2017). "qPCR analysis of endosome associated mRNA in fresh-frozen prostate cancer tissue demonstrated significantly increased expression of APPL1 in tissue from aggressive prostate cancer compared to non-malignant prostate and indolent prostate cancer tissue (P ≤ 0.01)." (PMID 26473288, 2015).
prostate carcinoma (continued). "Moreover, a greater number of APPL1-TβRI-ICD complexes were detected in sections from aggressive human prostate cancer tissues compared with less aggressive tumours, suggesting that increased expression of APPL1 could provoke alternative TGFβ signalling routes resulting in cancer progression." (PMID 26583432, 2016). "We investigated the subcellular localization of endogenous APPL1 and TβRI-ICD in human prostate cancer PC-3U cells using immunofluorescence staining and confocal imaging." (PMID 26583432, 2016). "APPL1 was also expressed in all epithelial cells in high-grade prostate intraepithelial neoplasia (HGPIN), suggesting that APPL1 participates in prostate cancer progression." (PMID 26583432, 2016). "HDAC3, which is upregulated in prostate cancer, facilitates lysine‐63‐chain polyubiquitination and phosphorylation of AKT in prostate cancer cells, a non‐nuclear effect mediated by AKT deacetylation at lysine 14 and 20 residues and HDAC3 interaction with the scaffold protein APPL1." (PMID 29572264, 2018). "In the current study, quantitation of gene signatures for the early endosomal genes APPL1, EEA1 and RAB5A, and analysis of the endosomal genes MYO1B, PDCD6IP and STX12 in prostate cancer patients expressing PSA ≤ 10 ng/mL, led to patient stratification into high and low-risk recurrence groups." (PMID 26473288, 2015). "As we observed that APPL1 promotes the transport of TβRI-ICD to the nucleus of prostate cancer cells and that this is connected to invasiveness, we investigated whether the APPL1-TβRI-ICD complex could be found in prostate cancer tissues." (PMID 26583432, 2016). "Indeed, Appl1-positive endosomes were detected throughout the cell cytoplasm of non-malignant control cells, whereas in prostate cancer cells these compartments were more concentrated at the cell periphery, particularly near the plasma membrane in cellular extensions/pseudopodia." (PMID 30459931, 2018). "The expression of APPL1 and EEA1 was significantly increased in primary prostate cancer when compared to non-malignant controls (P ≤ 0.05)." (PMID 26473288, 2015). "NOX2 co-located with Appl1, Rab5A, EEA1 and Rab7 endosome markers in non-malignant cells, but the co-location of NOX2 with these different endosome compartments was significantly increased in prostate cancer cells." (PMID 30459931, 2018).